PPIL6 (peptidylprolyl isomerase like 6)
Description:
Probable inactive PPIase with no peptidyl-prolyl cis-trans isomerase activity.
Synonyms: PPIase; bA425D10.6; MGC41939; dJ919F19.1; RSPH12
Tractability: Small molecule: a structure with a bound ligand is known.
Gene: Protein-coding gene on chromosome 6 (109,390,215 to 109,441,171, reverse strand). Ensembl gene ENSG00000185250.
Subcellular location (Human Protein Atlas): Vesicles; Nucleoli
Pathways (Reactome):
Disease: Dengue Virus-Host Interactions
Gene Ontology:
Molecular function: peptidyl-prolyl cis-trans isomerase activity; protein binding
Genetic constraint (gnomAD): Loss-of-function variants: 22 observed, 19.03 expected, observed/expected ratio (o/e) 1.16, 90% interval 0.82 to 1.64. The upper end of that interval is the gene's LOEUF score, 1.64, which puts it in group 6 of 6, group 1 being the genes least tolerant of losing a copy. Missense variants: 261 observed, 234.73 expected, observed/expected ratio (o/e) 1.11, 90% interval 1 to 1.23. Synonymous variants: 91 observed, 85.35 expected, observed/expected ratio (o/e) 1.07, 90% interval 0.9 to 1.27.
Homologues: Orthologues: chimpanzee PPIL6 (100% identical), macaque PPIL6 (97% identical), guinea pig PPIL6 (78% identical), rabbit PPIL6 (78% identical), pig PPIL6 (78% identical), dog PPIL6 (77% identical), rat Ppil6 (73% identical), mouse Ppil6 (72% identical), tropical clawed frog ppil6 (56% identical), zebrafish ppil6 (53% identical), Caenorhabditis elegans cyn-9 (24% identical), Drosophila melanogaster Cyp40 (24% identical). Paralogues in human: PPIE (29% identical), PPIL2 (26% identical), PPID (26% identical), NKTR (25% identical), PPIB (25% identical), PPIG (25% identical), PPIA (24% identical), PPIF (24% identical), PPIC (24% identical), PPWD1 (23% identical), PPIH (23% identical), PPIAL4C (22% identical), and 10 more.
Diseases named in the same sentence as PPIL6 in open-access papers:
PPIL6 is named in the same sentence as 3 diseases in open-access papers, as found by Europe PMC text mining. Sharing a sentence is not in itself a finding about the gene and the disease. The quoted sentences say what the papers report.
lung carcinoma (1 paper, 2026). "We highlight a potentially functional novel variant of PPIL6 in multiciliated cells underlying lung cancer risk through alternative splicing." (PMID 42039472, 2026).
PPIL6 also shares sentences with these, for which no sentence is quoted: Hypertension (1 paper); metabolic syndrome (1).